INS (insulin)
Diseases named in the same sentence as INS in open-access papers (continued):
Sharing a sentence is not in itself a finding about the gene and the disease.
diabetes (continued). "Although several reports discuss CrPic’s effects on body weight, blood glucose and insulin levels in diabetes, more investigation is required to better evaluate its anti-DN properties." (PMID 32143429, 2020). "Diabetes mellitus is a chronic disorder of carbohydrate, fat, and protein metabolism characterized by hyperglycemia resulting from defects in insulin secretion, insulin action, or both." (PMID 33100218, 2020). "As there have been few studies in which the effects of preoperative short-term insulin therapy and long-term insulin therapy were compared, the optimal duration of preoperative glycemic control in patients with diabetes is still unclear." (PMID 32993618, 2020). "Nitrate intake in diabetes and metabolic syndrome patients has been pointed out to ameliorate insulin sensitivity and vascular function." (PMID 32646062, 2020). "In particular, closed-loop systems for insulin delivery, such as the artificial pancreas, are regarded as cutting-edge technology in glucose management for diabetes." (PMID 32467827, 2020). "In the present studies, we determined the effects of long‐term diabetes on the metabolome of bladder detrusor in a rat model of streptozotocin‐induced type‐1‐diabetes and the ability of insulin treatment to normalize metabolic changes." (PMID 33200530, 2020). "BLK-MODY manifests as diabetes mellitus with an overweight phenotype and is managed with diet, OADs, or insulin." (PMID 33292863, 2020). "Most participants (92.1%) were prescribed oral medication for diabetes control, and only 6% (n = 79) used both medication and insulin." (PMID 33291678, 2020). "Diabetes is characterized by hyperglycemia related to autoimmune destruction of insulin-secreting β cells (type 1) or insulin resistance (type 2)." (PMID 32429597, 2020). "As far as the anti-diabetic effect is concerned, this is due to the inhibition of PTP1B, which negatively regulates insulin signaling; AR, which prevents diabetes complications; and α-glucosidase activities." (PMID 32932674, 2020). "The association between obesity, diabetes, and EC has led to the hypothesis that metformin may be effective in preventing and treating EC by the main effect in lowering blood glucose concentrations, increasing insulin sensitization, and reducing plasma fasting insulin levels." (PMID 32212801, 2020). "Type 1 diabetes mellitus (T1DM) is a globally-widespread disease that is characterized by a reduction in insulin production or the production of ineffective insulin." (PMID 32771009, 2020). "Diabetes mellitus is a metabolic disorder of carbohydrates, fats, and proteins that is characterized by impaired insulin secretion or a decrease in tissue sensitivity to insulin, leading to hyperglycemia." (PMID 32259003, 2020). "According to the definition claimed by the 2014 National Diabetes Statistics Report, “Diabetes is a group of diseases marked by high levels of blood glucose resulting from problems in how insulin is produced, how insulin works, or both." (PMID 32111208, 2020). "In transgenic mice, moderate expression of SIRT1 improves the glucose tolerance and insulin sensitivity in addition to resistance toward diabetes." (PMID 32082101, 2020). "Having a basal level insulin is thought to be important in preventing the development of several long-term complications in diabetes." (PMID 33202992, 2020). "The prevalence of diabetes was 25.1%, and of these participants, 2.7% were on insulin therapy, 60.7% received oral hypoglycemic agents (OHAs), 6.6% received both (insulin and OHAs), and 30% received no treatment." (PMID 32770968, 2020). "In 2001 medical framings of diabetes highlighted the biological impacts of increased insulin, emphasising its serious, risky and ‘deadly’ nature." (PMID 31951616, 2020). "As the treatment of diabetes, insulin, metformin, Xiaoke pill and gliclazide were the most frequently asked drugs." (PMID 32576159, 2020).
diabetes (continued). "In a type I diabetes model, the adenosine receptor agonist, NECA, reduced plasma glucose levels and ameliorated the diabetes-induced decrease in pancreatic insulin." (PMID 33050467, 2020). "Our findings also revealed a modulatory effect of the TaqIB variant on insulin, HOMA-IR, and QUICKI in response to dietary oil treatments only in diabetes patients." (PMID 33123324, 2020). "At present, the most common treatment for diabetes is still oral hypoglycemic drugs and insulin therapy." (PMID 32509879, 2020). "Diabetes mellitus is a heterogeneous metabolic disorder characterized by the presence of hyperglycemia due to deterioration of insulin secretion, defective insulin action, or both." (PMID 33585009, 2020). "Retinol-binding protein 4 activator decrease the concentration of RBP4 and thereby improves insulin sensitivity in diabetes." (PMID 32864980, 2020). "Chronic hyperinsulinemia is also a significant factor explaining cancer initiation and progression in patients with diabetes, due to the tumorigenic effect of insulin." (PMID 32962704, 2020). "Destruction or dysfunction of insulin-producing pancreatic beta-cells is a vital characteristic of diabetes." (PMID 33905469, 2020). "Ninety percent of patients with type 2 diabetes have a BMI greater than 23 kg/m2, and obesity and diabetes have common pathophysiology; impaired insulin production and action, impaired vascular function, and other metabolic anomalies." (PMID 32641021, 2020). "Insulin-treated patients with diabetes are likely to be older, have longer duration of diabetes, and have more comorbidities, including atherosclerotic disease." (PMID 33054769, 2020). "Medications used to control diabetes include insulin for type 1 diabetes and oral medications such as metformin and pioglitazone and ultimately insulin for type 2 diabetes." (PMID 33098389, 2020). "NMN treatment exerts beneficial effects on insulin secretion and insulin sensitivity in age- and diet-induced diabetes by restoring NAD+ biosynthesis." (PMID 33028824, 2020). "Restoration, however, of insulin-producing β-cells, as well as insulin-responsive cells, would be a logical strategy for the treatment of diabetes." (PMID 33198288, 2020). "Diabetes is an epidemic health concern in both developed and developing countries, characterized by impaired insulin production and function." (PMID 32405356, 2020). "Diabetes is a chronic disease that occurs when the body’s production of insulin is insufficient (type 1 diabetes) or when the insulin in the human body is ineffective (type 2 diabetes)." (PMID 32872490, 2020). "The thiazolidinedione class chemicals, including rosiglitazone, troglitazone, and PGZ can improve glucose uptake and insulin sensitivity via oral administration and thus used as a common anti-hyperglycemic treatment for type 2 diabetes mellitus." (PMID 33456717, 2020). "Chronic and acute beetroot juice supplementation, as a cost-effective strategy, is proposed to hold promises in controlling diabetes and insulin hemostasis, blood pressure and vascular function, renal health and the possible effect on microbiome abundance." (PMID 31921325, 2020). "The combined effects of quercetin with resveratrol in diabetic rats showed elevated serum blood glucose levels and insulin levels suggesting that co-treatment of quercetin with resveratrol has the potential for use as an alternative therapy for diabetes." (PMID 32694996, 2020). "Type 2 diabetes mellitus is characterized by the progression from insulin resistance to insufficient insulin secretion." (PMID 33123595, 2020). "Diabetes is characterized by elevated blood glucose levels, impaired insulin secretion, and/or peripheral resistance to insulin action." (PMID 32494038, 2020). "Groups B and C differed in terms of several baseline characteristics, including age, a previous diabetes diagnosis, hypertension, smoking, and insulin use." (PMID 32317703, 2020).
diabetes (continued). "Diabetes mellitus (DM) is a heterogeneous group of physiological disorders characterized by hyperglycemia resulting directly from insulin resistance, inadequate insulin secretion, or excessive glucagon secretion." (PMID 32542584, 2020). "Even though diabetes is defined by whole body insulin resistance, skeletal muscle as the greatest glycogen depot of the human body has still a particularly great role in the development and progression of the disease." (PMID 32024865, 2020). "Zinc transporter 8 (ZnT8) transports zinc ions for crystallization and storage of insulin in pancreatic beta-cells and ZnT8 dysfunction is involved in pathogenesis of diabetes." (PMID 32681069, 2020). "Results of 252 common targets were listed as (related with T2DM); TNF signaling pathway, insulin resistance, apoptosis, HIF-1 signaling pathway, PI3K-Akt signaling pathway, FoxO signaling pathway, insulin signaling pathway and type 2 diabetes mellitus." (PMID 33150068, 2020). "Other important applications are the treatment of diabetes and cardiovascular diseases: in the case of diabetes, new formulations are being explored in order to find less-invasive routes for insulin delivery and improving the drug delivery." (PMID 32033057, 2020). "Diabetes is a chronic condition that occurs when the body cannot produce enough insulin or respond properly to the insulin it does produce." (PMID 32194426, 2020). "A recent study reported that dapagliflozin treatment increased erythropoiesis and haematocrit in obese patients with T2DM receiving treatment with metformin (85% of patients), insulin (38%), sulfonylureas (38%) and pioglitazone (21%) for diabetes management." (PMID 33372185, 2020). "Patients with diabetes, history of thyroid disorders, and patients, who were taking medications that influence their blood glucose or insulin levels or modified thyroid function tests, were excluded." (PMID 32874434, 2020). "Appropriate concentration of selenium intake can act as an insulin minetic to attenuate diabetes, with the role of decreasing glucose and insulin tolerance, thus preventing hepatic insulin resistance." (PMID 33042976, 2020). "Pharmacy dispensing records from HIS were used to identify and track patients on at least one medicine or insulin for the management of diabetes." (PMID 32764027, 2020). "The in vitro combination of metformin and insulin was shown to decrease the adipogenesis impairment of preadipocytes that are derived from type 2 diabetes mellitus patients." (PMID 33092038, 2020). "A possible explanation for the small incidence of diabetes in our cohort lies in the improvement of insulin sensitivity determined by TNFi." (PMID 32370139, 2020). "Among children, out-of-pocket spending for diabetes-related supplies ($823) was higher than for insulin ($497)." (PMID 32478819, 2020). "Insulin is an effective therapeutic agent in the management of diabetes, but also sensitive to the external environment." (PMID 33046046, 2020). "Cancers share similar phenotypes with diabetes such as higher insulin and Insulin-like growth factor 1 (IGF-1) or leptin/adiponectin secretion and immune abnormalities." (PMID 32498358, 2020). "Type 2 Diabetes Mellitus (T2DM), as the most prevalent type, is caused by both an insulin resistance and an inadequate compensatory insulin secretory response." (PMID 32842548, 2020). "In another research, quercetin protected and retained the structure and integrity of the pancreatic β-cells while improving insulin secretion in streptozotocin-induced diabetes in rats." (PMID 33299532, 2020). "Only six participants were on anticoagulants (three on warfarin), four on insulin (7%) and 20 on oral agents for diabetes (33%), and 18 on a diuretics (30%)." (PMID 33036224, 2020). "Essentialvisits included pregnancy and diabetes, insulin starts, insulin pump and sensortraining, basic diabetes education to those newly diagnosed, and other visits asrequested by providers." (PMID 38603025, 2020).
diabetes (continued). "Diabetes is characterized by decreased insulin action (a decrease in either secretion or sensitivity) and increased availability of energetic substrates (i.e., glucose and FAs)." (PMID 32977483, 2020). "Diabetes is a disease in which blood glucose levels in the body rise higher than normal due to the pancreas is unable to produce sufficient hormone insulin." (PMID 32131831, 2020). "The highest prevalence of depression was observed among diabetes patients who are living in urban 32 (10.49%) and taking both oral and insulin medication 6 (21.43%)." (PMID 33145110, 2020). "T1DM (type 1 diabetes mellitus) is defined as a chronic autoimmune disorder characterized by the autoreactive T cell-mediated elimination of insulin-positive pancreatic beta-cells." (PMID 32973739, 2020). "It is clear that mitochondria play relevant roles in pancreatic β-cell secretion and a growing body of evidence links mitochondrial dysfunction to impaired insulin release in diabetes mellitus." (PMID 32528413, 2020). "From a pathophysiological perspective, insulin resistance (relative insufficient insulin), and impaired insulin secretion (insufficient insulin) are essential to diabetes occurrence." (PMID 33643038, 2020). "In diabetes, insulin-induced TGF-β1 upregulation by mobilization of the TGF-β type II receptor in DM-BMSCs are responsible for diabetes-related bone healing disorder." (PMID 32017705, 2020). "The beneficial effects of insulin as anabolic hormone should be taken into consideration when escalating diabetes therapy." (PMID 32733823, 2020). "ForLRRK2 andHCRT there are several instances in which clusters contained enrichment terms for insulin, diabetes, PD, other neurodegenerative disorders, and circadian processes but these did not achieve significance based on the corrected P value criteria." (PMID 34745571, 2020). "The drug metformin is the most widely used treatment for diabetes, and a modulator of gluconeogenesis and insulin sensitivity." (PMID 32713735, 2020). "Seventeen of the 37 FDA-approved receptor-binding peptides are insulin and its analogs, which are used for treating diabetes." (PMID 31941022, 2020). "Mean diabetes duration was 19 years with a mean A1C of 8.8%, 76% were insulin users, 43% had previous Ischemic Heart Disease (IHD), 24% previous CVD, and 14% reported a previous event of severe hypoglycemia requiring the aid of another." (PMID 32670196, 2020). "Oxidative stress is known to modulate insulin secretion and initiate gene alterations resulting in impairment of β-cell function and type 2 diabetes mellitus (T2DM)." (PMID 32599958, 2020). "The DNT include specific questions about sliding scale of insulin dosing, blood glucose monitoring, carbohydrate counting and exercise which are important tools for diabetes management." (PMID 32042313, 2020). "AA: Elevated (serum/plasma) AA level is an important early biomarker of glucose intolerance, insulin insensitivity and, subsequently, diabetes." (PMID 32708684, 2020). "The average duration of diabetes was 10.6 ± 7.8 years, including 44.8% of insulin therapy, 32.7% of drug therapy, and 22.4% of untreated patients." (PMID 32351563, 2020). "The platelets of diabetics have decreased sensitivity to insulin, potentially leading to reduced P2Y12 inhibition and increased platelet reactivity." (PMID 32754618, 2020). "There is pharmacological evidence that drugs like insulin and thiazolidinediones significantly suppress the free fatty acid flux and improves beta cell functions in diabetes." (PMID 32294959, 2020). "In conclusion, people with T2DM had an excess mortality risk, which was higher in women compared to men, younger people, in those who were diagnosed with T2DM at a younger age, had longer diabetes duration, and who required treatment with insulin." (PMID 32962295, 2020). "Our trial has several strengths, including the large enrolment of insulin-treated individuals with a long duration of diabetes." (PMID 31984443, 2020).
diabetes (continued). "A systematic review conducted by Cramer in the United States assessed patients with diabetes’ adherence with oral hypoglycemic agents and insulin and reported that 36% to 93% of the patients taking OHA remained on their treatment for 6-24 months." (PMID 32190485, 2020). "We first included the following variables in the model: age, sex, education level, smoking and drinking history, diabetes duration, insulin use, BMI, HbA1c, FBG, PBG, HDL-C, LDL-C, TC, TG, ApoA1, ApoB, sLPR1, and the LRP1 genotype." (PMID 33013281, 2020). "Descriptive statistics for the clinical characteristics of subjects with type 1 diabetes mellitus according to the sex-specific median insulin dose." (PMID 33370380, 2020). "In studies of Japanese patients, impaired insulin secretion seems the main driver of diabetes and prediabetes, with lesser role for insulin resistance." (PMID 32153503, 2020). "In subjects with diabetes duration of less than 5 years, fasting insulin decreased from 11.1 ± 4.1 to 6.3 ± 2.1 mcIU/ml, and HOMA-IR improved significantly from 3.39 ± 1.2 to 2.08 ± 0.8 after KRG treatment (p = 0.044 and p = 0.046, respectively)." (PMID 32025522, 2020). "Several studies in mice and rats have associated miR-29c-3p dysregulation with impaired glucose transporter expression and glycemic control in skeletal muscle, exacerbated vascular remodeling, and hepatic negative regulation of insulin signaling in diabetes." (PMID 31940853, 2020). "Continuous blood glucose monitoring is recommended in hospitalised COVID-19 patients with diabetes, with use of sliding scale insulin therapy." (PMID 32868984, 2020). "Patients with diabetes that received insulin were slightly younger; had higher body mass index; and had higher rates of dyslipidemia, hypertension, chronic lung disease, and previous stroke." (PMID 33118731, 2020). "Multiple genes involved in glycolysis are upregulated in diabetes and interfere with normal insulin secretion." (PMID 32859966, 2020). "Mean diabetes duration of the population was 10.2 ± 6.9 years and 57.1% of the patients were on insulin treatment." (PMID 31655535, 2020). "During the 4-week intervention period following diabetes onset, insulin-treated mice maintained on an HFD exhibited significantly improved glucose tolerance test results compared to sham-treated animals." (PMID 33105611, 2020). "The strengths of insulin administration in the treatment of diabetes are profound, but these need to be balanced against several serious shortcomings of its extended use." (PMID 33167495, 2020). "At present, there are many methods of drug administration for diabetes treatment, such as transdermal delivery, oral delivery, nasal insulin delivery, and pulmonary delivery." (PMID 32850735, 2020). "Diabetes mellitus (DM) is a chronic metabolic condition that occurs when the body cannot use insulin." (PMID 32087714, 2020). "An exercise intervention improves glucose homeostasis and insulin sensitivity in patients with pre-diabetes, which is closely related to changes in intestinal flora and its ability to ferment proteins and carbohydrates." (PMID 32756447, 2020). "Other factors included the patient’s work schedule and lifestyle factors (22.5%), the availability of nurses, diabetes educators and others to follow the insulin treatment (12.7%) and the cost of insulin (4.2%)." (PMID 32957991, 2020). "It has become clarified in recent years that the essential nature of diabetes mellitus consists in insulin resistance, and insulin-sensitizing agents have been marketed in succession as drugs for treatment of insulin resistance." (PMID 33270683, 2020). "The Diabetes Injection Device Preference Questionnaire (DID-PQ) was designed to assess patient preference between two non-insulin injection devices." (PMID 33296064, 2020). "In our evaluation a younger diabetes population is assumed, with individuals who truly have monogenic diabetes being more likely to be misdiagnosed with type 1 and receive insulin." (PMID 32193268, 2020).